GJB2 (gap junction protein beta 2)
Diseases named in the same sentence as GJB2 in open-access papers (continued):
Sharing a sentence is not in itself a finding about the gene and the disease.
deafness (continued). "The causative variants in deafness genes were confirmed, namely eight with bi-allelic GJB2 variants, one with bi-allelic SLC26A4 variants, and one with bi-allelic OTOF variants." (PMID 34943631, 2021). "Due to the difficulty in obtaining human pathological specimens, the mechanism of GJB2 gene mutation-induced deafness is mainly studied using the GJB2 gene knock-down mouse model." (PMID 35345836, 2021). "Mutations in the GJB2 gene linked to deafness have been found in all Cx26 domains and they can compromise different stages of the Cx26 life cycle." (PMID 33466560, 2021). "Another common polymorphism in GJB2 gene, including V153I, is effective in varying degrees of deafness due to a change in the encoding region of this mutation and its integration with other mutations in this gene or other genes." (PMID 33912482, 2021). "Targeted next-generation sequencing of 139 known deafness-related genes were performed in 44 probands with mono-allelic GJB2 mutations." (PMID 31992338, 2020). "The frequency of heterozygotes/carriers is similar to another pathogenic variant c.71G>A (p.W24*) in GJB2, regarded as the most frequent variant causing deafness in Roma populations." (PMID 32847582, 2020). "With China having approximately one fifth of the world’s population, evaluating the molecular epidemiology of GJB2 mutations in Chinese deaf patients has important implications in guiding genetic testing for deafness." (PMID 31992338, 2020). "One example associated with HL is heterozygous GJB2 (Cx26) mutations resulting in an autosomal dominant syndromic HL, keratitis-ichthyosis-deafness (KID), and a homozygous GJB2 mutation causing ARNSHL28–30." (PMID 32728090, 2020). "For example, the digenic interaction that underlies the cause of deafness in individuals carrying a single mutation at the GJB2 locus along with a deletion in the functionally related GJB6 gene." (PMID 31898538, 2020). "In this study, we characterized the clinical features of 12 Chinese Han deaf families in which mutations in common deafness genes GJB2, SLC26A4, and MT‐RNR1 were excluded." (PMID 32048449, 2020). "GJB2 [encoding connexin 26 (Cx26)] is the most common deafness gene, and its mutations are responsible for a quarter of hereditary deafness cases worldwide." (PMID 33505961, 2020). "High prevalence of the GJB2-associated deafness makes the GJB2 gene testing essential for the establishment of genetic diagnosis of hearing loss." (PMID 32708339, 2020). "In this light, we recruited a series of Chinese Han deaf families that were preexcluded from mutations in common deafness genes GJB2,SLC26A4, and MT‐RNR1." (PMID 32048449, 2020). "The 12 Chinese probands have been previously excluded for mutations in common deafness genes GJB2,SLC26A4, and MT‐RNR1 by Sanger sequencing." (PMID 32048449, 2020). "In other words, deafness can be caused by the addition of a mutation in one allele of GJB2 and one allele of GJB6 or GJB3, indicating an interaction of these connexins in the cochlea." (PMID 33126609, 2020). "It is has been shown that digenic inheritance of recessive deafness by mutations in GJB2 and GJB6, or GJB2 and GJB3 can occur." (PMID 33126609, 2020). "Targeted next-generation sequencing of 415 deafness-related genes identified a homozygous c.235delC (p.L79Cfs∗3) variant in GJB2 as the pathogenic cause of hearing loss for the mother III-2." (PMID 32908489, 2020). "Recent comprehensive next‐generation sequencing (NGS) analysis has helped clarify genetic epidemiology; i.e., GJB2 is the predominant deafness‐causing gene, with the other common genes being CDH23, SLC26A4, MYO15A, COL11A2, and MYO7A." (PMID 32027099, 2020). "The use of inherited disease genes sequencing panel identified the causative and novel variants in deafness related genes (GJB2, MYO7A, CDH23, TH and EVC2) in deaf brothers." (PMID 30881389, 2019).
deafness (continued). "The deafness-linked GJB2 mutations include at least 93 truncation mutations, 239 point mutations that are known to cause either non-syndromic or syndromic deafness." (PMID 31827424, 2019). "Common deafness-associated genes in the Taiwanese patients assessed, in the order of prevalence, included GJB2, SLC26A4, OTOF, MYO15A, and MTRNR1, which were similar to those found in other populations." (PMID 31581539, 2019). "It is concluded that in addition to novel mutations in MYO7A, TH and EVC2, the CDH23 and GJB2 can also be responsible for deafness in the family with consanguineous marriages." (PMID 30881389, 2019). "The frequency of carrier mutations in the GJB2 gene, which is the most prevalent cause of autosomal recessive deafness, is reported to be approximately 2% in the normal hearing population." (PMID 30867468, 2019). "The GJB2 frameshift mutations c.235delC (rs80338943) and c.299_300delAT (rs111033204) found in Tuvinian patients are well known deleterious GJB2 variants associated with deafness." (PMID 31195736, 2019). "On the other hand, in our cohort, mutations in the GJB2 gene, which is the most prevalent cause of autosomal recessive deafness, were found to follow pseudodominant inheritance in 15 (10.1%) of 149 probands showing all forms of inheritance." (PMID 30867468, 2019). "The accumulation of data demonstrates that mutations in GJB2, which encodes Cx26, account for approximately half of all inherited prelingual non-syndromic deafness cases in both European and East Asian populations." (PMID 31827424, 2019). "Common deafness-associated genes in Taiwanese families, in order of prevalence, included GJB2, SLC26A4, OTOF, MYO15A, and MTRNR1, which are similar to those found in other populations." (PMID 31581539, 2019). "The propositus’ deafness gene microarray results demonstrate a single heterozygous c.235delC pathogenic variant in the GJB2 gene's." (PMID 31852093, 2019). "Mutations in GJB2 gene are a major causes of deafness and their spectrum and prevalence are specific for various populations." (PMID 30086704, 2018). "From the epidemiological perspective, mutations of three deafness genes: GJB2, SLC26A4, and MT-RNR1, are much more prevalent than those of other genes worldwide." (PMID 30576380, 2018). "The goal of this research is to explore the genetic cause of a Chinese deafness pedigree who was excluded of GJB2, SLC26A4, or MtDNA12SrRNA variants." (PMID 29849560, 2018). "Several different mouse models have been established to study the mechanism through which GJB2 mutations lead to deafness, but this process is still poorly understood." (PMID 30518746, 2018). "The first deafness associated gene in the DFNB1 locus, the GJB2 gene (GenBank M86849, MIM 121011) coding the gap junction protein, Connexin 26 (Cx26), was reported in 1997." (PMID 29921236, 2018). "In our series, as in most of published studies, prior to comprehensive genetic testing, patients were prescreened for common deafness mutations (in our cohort, GJB2/GJB6, OTOF and MT-RNR1, selected for their high prevalence in Spain)." (PMID 29986705, 2018). "The increased cav2 level contributed dramatically to the progression of the GJB2 –associated deafness." (PMID 29760588, 2018). "Mutations in the GJB2 gene (which encodes Connexin26 (Cx26)) account for a quarter of all cases of non-syndromic deafness in different populations." (PMID 30518746, 2018). "Germline missense mutations in GJB2 encoding connexin (Cx) 26 have been found in keratitis, ichthyosis and deafness (KID) syndrome." (PMID 30150638, 2018). "Testing for this mutation explained deafness in 45% of Czech patients with GJB2 monoallelic mutations." (PMID 30344259, 2018). "Mutations in the GJB2 gene (which encodes Connexin26 (Cx26)) account for about a quarter of all cases of non-syndromic deafness." (PMID 30518746, 2018).
deafness (continued). "In this present study we have used an allele-specific PCR-based universal array designed to simultaneously screen nine deafness associated variants in the GJB2, GJB6, SLC26A4, MT-RNR1 and MTTS genes that are common in patients of European descent." (PMID 28273078, 2017). "A hereditary deafness gene mutation screening was performed to identify the mutation sites in four deafness-related genes (GJB2, GJB3, 12S rRNA, and SLC26A4)." (PMID 28335750, 2017). "We carried out PCR, restriction enzyme based screening, and sequencing of 132 Syrian patients diagnosed clinically with hereditary deafness for different GJB2 mutations." (PMID 29362677, 2017). "Three patients were tested in early childhood for GJB2 gene mutations, since this gene is deemed to be the leading cause for hereditary deafness within the European population." (PMID 29142287, 2017). "The carrier rate of GJB2 mutations known to cause Cx26 related deafness is greater than 3% of all individuals in the United States and is among the highest of any disease." (PMID 26965868, 2016). "Current genetic testing applies Sanger sequencing and microarray approaches primarily for detecting mutations in GJB2 and for a small number of other known common deafness genes." (PMID 27082237, 2016). "Of these 27 patients, 8 had mitochondrial mutations together with mutations in other deafness genes, and 6 carried bi-allelic mutations in the GJB2 gene together with mutations in other deafness genes." (PMID 27627659, 2016). "First, mutations of the common deafness genes GJB2, SLC26A4, and mtDNA 12SrRNA were investigated in the affected family members by sequencing." (PMID 26832775, 2016). "Of these variants, the c.35delG is the most prevalent GJB2-deafness-causing mutation in European populations, while c.235delC and c.167delT are the most frequent variants in Eastern Asian populations and Ashkenazi Jewish families, respectively." (PMID 26043044, 2015). "More than 150 different GJB2 variants have been identified, including missense, nonsense and frameshift mutation (The Connexin-deafness Homepage." (PMID 26043044, 2015). "The contribution of GJB2 to the genetic load of deafness and its mutation spectra vary from mild to profound." (PMID 26061264, 2015). "While the GJB2 gene mutations associated with skin symptoms all cause deafness, mutations in the GJB6 gene result in skin disease, usually without hearing impairment." (PMID 25575739, 2015). "Our previous study performed mutation screening of common deafness genes GJB2, SLC26A4 and MT-RNR1 in seven consanguineous Uyghur families and detected bi-allelic SLC26A4 mutations in three of them." (PMID 26011067, 2015). "Taken together, we identified 9 GJB2 variants in this large cohort of Han Chinese population to be pathogenic, including the 5 known deafness-associated mutations (p.G12V, p.V37I, p.V95M, p.R143W and p.E147K)." (PMID 26043044, 2015). "A genotype-phenotype correlation analysis was performed among 4 probands carrying the 4 putative deafness-associated GJB2 mutations." (PMID 26043044, 2015). "Among the >100 known forms of non-syndromic deafness with identified genetic loci, by far the most common and best characterized is the one associated with GJB2 (OMIM 121011), the gene encoding connexin 26 (Cx26)." (PMID 26492081, 2015). "Using this strategy, mutations in the rare deafness genes can be detected in between 23.2% and 62.5% of deaf patients that were excluded from mutations in GJB2, SLC26A or MT-RNR1." (PMID 26011067, 2015). "The c.35delG mutation in the GJB2 gene was identified in 15.6 % of the patients, and in 11.1 % of cases, this mutation was found in homozygosis, explaining the etiology of deafness." (PMID 26399936, 2015). "There were 20 patients (12.9%) confirmed to have GJB2 deafness-causing mutations: 13 homozygotes (nine with the c.235delC allele and four with the c.109G>A allele) and seven compound heterozygotes." (PMID 26252218, 2015).
deafness (continued). "In this study, we investigated the genetic etiology of nonsyndromic deafness in four consanguineous and two multiplex Uyghur families in which mutations in common deafness genes GJB2, SLC26A4 and MT-RNR1 were excluded." (PMID 26011067, 2015). "The contribution of Gap junction beta-2 protein (GJB2) to the genetic load of deafness and its mutation spectra vary among different ethnic groups." (PMID 26061264, 2015). "All patients underwent mutation screening of three common deafness genes: GJB2, SLC26A4 and the mitochondrial 12S rRNA gene." (PMID 26397989, 2015). "Summary of clinical and molecular data for 4 Han Chinese subjects carrying the putative deafness-associated mutations in GJB2 gene." (PMID 26043044, 2015). "More than 50% of the families carry mutations in GJB2 while mutations in MYO15A account for about 5% of recessive deafness." (PMID 24949729, 2014). "In fact, digenic inheritance of nonsyndromic deafness caused by mutations in the GJB2 gene and other connexin genes, such as GJB3, GJB6, GJB4, or GJA1, have been previously reported in several deaf patients." (PMID 25388789, 2014). "Although TMPRSS3 mutations seem to be less common than GJB2 mutations, TMPRSS3 mutations lead to inheritable deafness, especially when common GJB2, SLC26A4 and 12S rRNA mutations are excluded." (PMID 25474651, 2014). "We propose the existence of an underlying mechanism to explain the disruption of the cyto-architecture in the organ of Corti in prelingual deafness caused by the Gjb2 mutation." (PMID 24387126, 2014). "A large number of reports on human GJB2 mutations linked to prelingual deafness indicated loss-of-function mutations that effectively null the utility of Cx26 in the cochlea." (PMID 25013956, 2014). "Most GJB2 mutations produce non-syndromic deafness, but a subset produces syndromic deafness in which profound hearing loss is accompanied by a diverse array of infectious and neoplastic cutaneous disorders that can be fatal." (PMID 25386120, 2014). "For example, in hereditary deafness with mutations of specific genes, such as, GJB2, SLC26A4, OTOF, COCH, and MYH9, mitochondrial mutations, CI is expected to provide successful results." (PMID 25373420, 2014). "In China, routine clinical diagnostic tests for deafness have consisted of the GJB2, SLC26A4, and mitochondrial 12S rRNA genes." (PMID 24586623, 2014). "The 427C>T mutation was first reported in the GJB2 gene, with the mutation causing the amino acid at position 143 to change from arginine to tryptophan, thereby causing autosomal recessive deafness." (PMID 24348793, 2014). "Cord blood was used for the screening of deafness-susceptibility genes, namely the GJB2, SLC26A4 and mitochondrial 12S rRNA (MTRNR1) genes." (PMID 24348793, 2014). "There are in total 31.46% of the patients with NSHL carry deafness-causing mutation in GJB2 or mtDNA 12S rRNA genes." (PMID 23826813, 2013). "The 235delC appeared to be the most common deafness-causing GJB2 mutation (102/658, 15.50% ) with the highest allele frequency." (PMID 23826813, 2013). "Pre-screening of mutations in three common deafness genes, GJB2, SLC26A4 and MT-RNR1, was performed in all 190 deaf probands by Sanger sequencing." (PMID 23767834, 2013). "Similar to other previous reports of China, our study showed that GJB2 mutations were an important cause of NSHL in Jiangsu deafness populations, and the most common GJB2 mutation detected in our study group was the c.235delC (102/658; 15.50% )." (PMID 23826813, 2013). "I203T and I203K mutations have been observed in the GJB2 gene in several populations, where studies have been conducted to establish the cause of deafness of several individuals, both adults and newborns." (PMID 23967136, 2013). "A total of 164 participating subjects carried one type of the four common deafness-causing mutations in GJB2 gene in the heterozygous state, and the carrier rate was 2.26% in the population." (PMID 23718755, 2013).
deafness (continued). "Mutations in the connexin 26 (GJB2) gene rank among the most frequent causes of non-syndromic deafness in different populations, while delGJB6-D13S1830 mutation located in the DFNB30 locus is known to cause sensorineural hearing loss." (PMID 23503914, 2013). "Probands with mutations in commonly screened deafness genes GJB2, SLC26A4 and MT-RNR1 were pre-excluded by Sanger sequencing." (PMID 23767834, 2013). "There are in total 31.46% of patients with NSHL carry deafness-causing mutations in GJB2 or mtDNA 12S rRNA gene." (PMID 23826813, 2013). "We focused on the presumably rare deafness genes by pre-exclusion of mutations in three commonly screened deafness genes GJB2, SLC26A4 and MT-RNR1." (PMID 23767834, 2013). "As previously reported, in a substantial proportion of patients our Invader techniques and additional direct sequencing revealed only one mutant GJB2 or SLC26A4 allele causing deafness by recessive pattern." (PMID 22384008, 2012). "This is the case for c.35delG mutation in GJB2 that causes deafness and is widely spread in Europe and around the Mediterranean basin." (PMID 22908982, 2012). "Among the deafness genes situated on the present diagnostic panel, mutations were most frequently found in the GJB2 gene." (PMID 22384008, 2012). "The c.35delG mutation, a deletion of a guanine in the GJB2 coding sequence, is the most common recessive deafness-causing mutation in Europe." (PMID 23074689, 2012). "The single-nucleotide guanine deletion (35delG) of the GJB2 gene coding for connexin 26 was shown to be the main genetic cause of autosomal recessive deafness among Europeans." (PMID 22567152, 2012). "Mutations in the GJB2 gene are the most frequent in nonsyndromic recessive deafness, accounting for up to 50% of the cases." (PMID 23074689, 2012). "In GJB2 screening, 46 (17.4%) samples from deafness subjects had mutations of one or both alleles of the GJB2 gene." (PMID 22384008, 2012). "The most frequent GJB2 anomaly causing deafness in Europeans and white Americans is deletion of one guanine within the six-guanine string at the beginning of the second GJB2 exon (positions 30–35), the so-called 35delG mutation (rs80338939)." (PMID 22567152, 2012). "The carrier frequencies of deafness-causing GJB2 mutations in our case group were 0.74% for 176-191del16, 27.41% for 235delC, 4.44% for 299-300delAT, 1.48% for T123N and 1.48% for 504insGCAA, respectively." (PMID 23554706, 2011). "To date, routine clinical diagnostic tests for deafness in the Middle East have consisted of restriction enzyme analysis of the two common GJB2 mutations, and on occasion, DNA sequencing of the GJB2 coding region." (PMID 21917145, 2011). "This review provides an overview of recent findings concerning pathogenesis of syndromic deafness imputable to GJB2 mutations with an emphasis on relevant clinical genotype-phenotype correlations." (PMID 22547955, 2011). "In fact, mutations in the GJB2 gene coding for Cx26 can cause a variety of deafness and hereditary hyperproliferative skin disorders in humans." (PMID 22547955, 2011). "The NGS targeted 4 deafness-associated mutations commonly found in the Taiwanese population, including p.V37I (c.109G>A) and c.235delC of the GJB2 gene, c.919-2A>G of the SLC26A4 gene, and mitochondrial m.1555A>G of the 12S rRNA gene." (PMID 21811586, 2011). "The presence of the known 235DelC/299DelAT mutation in the GJB2 gene in the subject ZX039-IV-1 carrying the 1413T > C mutation indicated its role in the deafness phenotype." (PMID 21205314, 2011). "To examine if the GJB2 gene contributed to a deafness phenotype, we performed the mutational screening of GJB2 gene in 39 subjects carrying the known deafness-associated 12S rRNA mutations and 5 subjects carrying one of 5 putative 12S rRNA mutations." (PMID 21205314, 2011). "The 235delC appeared to be the most common deafness-related GJB2 mutation (37/135, 27.41%) with the highest allele frequency of 20.37%." (PMID 23554706, 2011).